FOXP3 (forkhead box P3)
Diseases named in the same sentence as FOXP3 in open-access papers (continued):
Sharing a sentence is not in itself a finding about the gene and the disease.
autoimmune disease (continued). "Adoptive transfer of in-vitro induced Foxp3+ T regulatory (iTreg) cells forms an attractive approach to therapeutically restore the balance when healthy immunity is disturbed, i.e. in autoimmune disease." (PMID 25108241, 2014). "Impairment of the mTORC1 pathway in Treg via selective genetic deletion of Raptor, an obligatory component of mTORC1, in the CD4+ FOXP3+ compartment, led to the early onset of a fatal autoimmune disease in mice." (PMID 25477880, 2014). "The conditions that induce human Foxp3+ Tregs to secrete different effector cytokines and the role of these cells in infections, cancer, and autoimmune diseases remain to be fully established." (PMID 25566245, 2014). "Foxp3 transduction of naive CD4+ T cells can convert these cells into functional Foxp3+ Treg cells that prevent or suppress the development of a number of autoimmune diseases in animals." (PMID 25152867, 2014). "Adoptive transfer of antigen-specific, in vitro-induced Foxp3+ Treg (iTreg) cells protects against autoimmune disease." (PMID 25108241, 2014). "Dicer knockout mice as well as mice with conditional knockout of Dicer in FoxP3+ cells develop severe autoimmune diseases." (PMID 24521175, 2014). "The autoimmune disease that lacks functional FOXP3, observed in human and in mice, indicates that this transcription factor has a crucial role in the regulation of T-cell function." (PMID 24877082, 2014). "CD4+Foxp3+ T regulatory (Treg) cells control many facets of immune responses ranging from autoimmune diseases, to inflammatory conditions, and cancer in an attempt to maintain immune homeostasis." (PMID 23874336, 2013). "T regulatory (Treg) cells expressing the transcription factor FoxP3 play an indispensible role in the maintenance of peripheral homeostasis and avoidance of autoimmune disease." (PMID 23593464, 2013). "The HCV-induced Tim-3/Gal-9-mediated imbalance of IL-12/IL-23 production by M/MФ during viral infection promotes TH17 cell as well as Foxp3+ Treg differentiation and development, perhaps contributing to persistent infection and autoimmune disorders." (PMID 23967307, 2013). "CD4+CD25+ Tregs were important in the prevention of autoimmune diseases and were found to express high levels of Foxp3." (PMID 23781248, 2013). "Treg cells, defined by the expression of CD4, CD25, and the key transcription factor Foxp3, have an important role in immune suppression and protection from autoimmune diseases." (PMID 24177566, 2013). "In human autoimmune diseases, T helper type-I-like Foxp3+ Tregs depend on the availability of the Th1-inducing cytokine IL-12." (PMID 23589107, 2013). "Regulatory T (Treg) cells are a subset of CD4+ T cells that specifically express the forkhead box P3 (Foxp3) transcription factor and play an essential role in dampening immune responses and preventing autoimmune disease (10, –, 12)." (PMID 23926350, 2013). "CD4+CD25+Foxp3+ Treg cells are a specialized Th cell subset that is engaged in maintaining peripheral tolerance, preventing autoimmune diseases, and limiting chronic inflammatory diseases by suppressing and regulating the effector function of Th cells." (PMID 24187560, 2013). "In humans, FOXP3 MFI also was related with suppression mediated by Treg in the autoimmune disease model." (PMID 24244424, 2013). "The potential of CD4+Foxp3+ Treg to influence the course of immune-mediated disorders and autoimmune diseases has become a major focus of advanced cellular immunotherapy." (PMID 23446139, 2013). "These mice develop spontaneous autoimmune disease from about 3–4 months of age, in contrast to conditional knockout of Dicer in Foxp3+ cells (Foxp3CreDicerfl/fl), which results in spontaneous autoimmune disease that is fatal by 4 weeks of age." (PMID 23818888, 2013).
autoimmune disease (continued). "Endowed with highly suppressive machinery, it is now well established that CD4+Foxp3+ Treg cells regulate a diverse array of immune responses ranging from autoimmune disease, allergies, and transplant rejection, to infections and cancers." (PMID 23874336, 2013). "T regulatory (Treg) cells expressing the transcription factor FoxP3 play a key role in protection against autoimmune disease." (PMID 23593464, 2013). "The confirmation of FOXP3 function derives from a recent discover: a mutation of the FOXP3 gene may lead to a pediatric syndrome characterized by the association of several different autoimmune diseases (IPEX Syndrome: immune dysfunction, poliendocrinopathy, enteropathy, and X-linked)." (PMID 24063002, 2013). "Defects in the transcription factor FoxP3, which defines the Treg lineage, result in multiple autoimmune diseases and atopy demonstrating the central role of FoxP3+CD4 cells in immune homeostasis." (PMID 23737654, 2013). "Treg cells expressing the FoxP3 transcription factor play a crucial role in the protection against undesired T cell activation and autoimmune disease, while still allowing a fast and effective immunological response to pathogens." (PMID 23593464, 2013). "Tregs are characterized by the expression of a specific transcription factor, forkhead box P3 (Foxp3), and play a key role in the autoimmune diseases." (PMID 23781248, 2013). "A recent study has shown the class I/II HDAC inhibitor TSA promoted Foxp3 expression and the generation and function of Tregs in an autoimmune disease murine model with C57BL/6 mice." (PMID 22303460, 2012). "On the one hand FTS inhibits cancer cell proliferation and tumor growth; on the other hand it upregulates Foxp3+ Tregs, thereby attenuating autoimmune disease but inhibiting the antitumor activity of CTLs." (PMID 22323550, 2012). "Although Foxp3+ Tregs have been found to have positive effects in autoimmune diseases (inhibition of T effector cells and attenuation of the disease), their accumulation in tumors is associated with unfavorable clinical prognosis." (PMID 22323550, 2012). "Our investigation revealed that the mRNA expression of forkhead box P3 (Foxp3, a Tregs-specific transcriptional factor) was higher in IgG4-related disease than in classical autoimmune diseases." (PMID 21994885, 2012). "In multiple sclerosis (MS) and other autoimmune diseases, the autoreactive T cells overcome the resistance provided by the regulatory T cells (Tregs) due to a decrease in the number of Foxp3-expressing Tregs." (PMID 23284794, 2012). "This unique ability can make FOXP3+ Tregs to control immune responses to prevent development of autoimmune disease, immunopathology, and allergy, as well as to maintain allograft tolerance and fetal-maternal tolerance during pregnancy." (PMID 22536257, 2012). "A newly identified subset of the CD4+Foxp3+ Tregs, the CD39+ Tregs, has been associated with viral infections and autoimmune diseases." (PMID 22489829, 2012). "Foxp3+ regulatory T cells play important roles by inducing anti-inflammatory IL-10-producing T cells in various autoimmune diseases." (PMID 22110705, 2011). "Importantly, the use of RAPA and ATRA in Treg culture increased the percentage of Tregs with demethylated FOXP3 alleles suggesting that these Tregs are more likely to remain as Tregs once re-infused in the patient and provide long lasting and effective control of autoimmune disease." (PMID 21253593, 2011). "CD8α− DCs from GM-CSF treated mice that produce significantly lower levels of pro-inflammatory cytokines IL-12 and IL-1β compared to the DCs from control mice can induce and/or expand Foxp3+ Tregs and suppress autoimmune diseases." (PMID 21779356, 2011). "Even if depletion of CD4+CD25+ T cell population leads to autoimmune disease in nude mice, recent findings show that up to one-third of FoxP3+ cells in a naïve mouse are CD25− and will remain unaffected by anti-CD25 monoclonal antibody (mAb) administration)." (PMID 21731726, 2011).
autoimmune disease (continued). "The CD4+ CD25+ regulatory population of T cells (Treg cells), which expresses the forkhead family transcription factor (Foxp3), is the key component of the peripheral tolerance mechanism that protects against a variety of autoimmune diseases." (PMID 21162738, 2010). "Foxp3-positive regulatory T Cells (Tregs) are important for maintaining peripheral tolerance, preventing autoimmune diseases and limiting chronic inflammatory diseases." (PMID 21192826, 2010). "It is widely accepted that FoxP3+ regulatory T cells(Treg) play critical roles in pathogenesis of various of kinds of autoimmune diseases including human RA." (PMID 20537152, 2010). "Both naturally arising Foxp3+ and antigen-induced Foxp3− regulatory T cells (Treg) play a critical role in regulating immune responses, as well as in preventing autoimmune diseases and graft rejection." (PMID 19924236, 2009). "CD4+CD25+FOXP3+ Regulatory T cells (Treg) play a central role in the immune balance to prevent autoimmune disease." (PMID 19779623, 2009). "CD4+CD25+FOXP3+ regulatory T cells (Treg) are of critical importance for the maintenance of immune homeostasis, as numerous experimental mouse models for autoimmune diseases correlate the presence of functional Tregs with amelioration of disease severity." (PMID 19779623, 2009). "Intrinsic Treg, i.e. specifically described as CD4+CD25+foxP3+ T cells, which prevent autoimmune disease, are expanded in NOD mice only after blocking CD40–CD154 interaction." (PMID 18446238, 2008). "Removal of the thymus from neonatal mice has been shown to result in a multiple organ autoimmune disease phenotype that can be prevented by introducing the FoxP3+ Treg population to the animal." (PMID 16579866, 2006). "The characterization of the molecular targets of Foxp3 and the mechanism(s) utilized by Foxp3 to support Treg development and function will aid in our understanding of the role Tregs play in the pathogenesis of human autoimmune disease." (PMID 16652169, 2006). "For instance, an increased p-S6 expression in Tregs has been observed under inflammatory conditions, in tumor microenvironments, and during autoimmune disease progression, often coinciding with diminished FOXP3 expression and acquisition of effector-like properties." (PMID 40852720, 2025). "Aberrant hypermethylation of the Foxp3-TSDR, often driven by dysregulated DNA methyltransferases like DNMT1, disrupts Treg differentiation and function, contributing to the pathogenic Th17/Treg imbalance observed in autoimmune diseases, including SLE." (PMID 40918088, 2025). "Strategies targeting FOXP3 splicing isoforms in Tregs may provide potential new therapeutic approaches for the treatment of autoimmune diseases, inflammation, and cancer." (PMID 40002189, 2025). "Several studies have highlighted the role of genetic variants within the FOXP3 gene, including rs2280883 and rs3761548, in influencing FOXP3 expression and function, thereby altering Treg activity and disrupting immune homeostasis in inflammatory and autoimmune diseases." (PMID 40076417, 2025). "Due to the ongoing or intermittent release of tissue-specific factors governed by self- or infection-specific antigens and epigenetic control of FOXP3 during chronic inflammatory processes of autoimmune disease, Treg cells may acquire a conventional phenotype." (PMID 40804844, 2025). "FOXP3 targeting may represent a complementary strategy to improve the functional resilience of CAR T cell therapies in cancer or autoimmune disease." (PMID 40955316, 2025). "Tregs, which exhibit upregulated expression of the transcription factor Forkhead box protein P3 (Foxp3), play a crucial role in suppressing excessive immune responses, including autoimmune diseases, making them central negative regulators of the adaptive immune system." (PMID 38606172, 2024).
autoimmune disease (continued). "Furthermore, a recent paper reported that in patients with FOXP3 mutation, T cells clonally expand to induce tissue-specific inflammation even in sterile conditions, suggesting that Treg depletion could cause activation of self-reactive T cells to induce autoimmune disease." (PMID 39221254, 2024). "Additionally, it has been demonstrated that the Ser418 phosphorylation site, which is located at the C-terminus of Foxp3, is phosphorylated in autoimmune diseases." (PMID 38919615, 2024). "The depletion of FOXP3+ CD25+ CD4+ Tregs leads to similar autoimmune diseases in rodents." (PMID 38674427, 2024). "The targeted inhibition of UHRF1 by DPPA3 or PRMT6 proteins may mitigate the suppressive impact of DNMTs on FOXP3+Tregs, thereby offering promising prospects for the treatment of autoimmune diseases." (PMID 39144146, 2024). "Furthermore, clinical trials exploring low-dose IL-2 administration in patients with autoimmune diseases have consistently reported an expansion of FOXP3+ Treg populations, although the overall clinical responses have been variable." (PMID 39697333, 2024). "Do ex-FoxP3 Tregs play a role in the pathogenesis of autoimmune diseases?" (PMID 39000278, 2024). "Additionally, genes involved in immune regulation and tolerance, such as FOXP3, IL2RA, and TNF receptor superfamily member 25, have also been linked to autoimmune disease susceptibility." (PMID 39062908, 2024). "Significantly, human X-linked and autoimmune diseases, including immune system disorders, several endocrine disorders, intestinal diseases, X-linked syndrome (IPEX syndrome), and others, can result from the functional loss or mutation of the Foxp3 gene." (PMID 38919615, 2024). "In comparison, the absence of Foxp3 will lead to the loss of Treg function, which is closely associated with severe autoimmune diseases in humans and rodents." (PMID 36911741, 2023). "Various studies have shown that pharmacological targeting of enzymes involved in PTMs can significantly influence the PTMs of Foxp3; thus, it may influence the progression of cancers and/or autoimmune diseases." (PMID 37936703, 2023). "Forkhead box protein 3 (Foxp3)+ regulatory T cells (Tregs) play a fundamental role in maintaining immune homeostasis and self-tolerance, and their instability and dysfunction result in excessive and uncontrolled immune responses leading to autoimmune diseases." (PMID 37594540, 2023). "Moreover, they showed that GMSCs not only express ENTPD1 but also enhance the frequency of ENTPD1+Foxp3+ Tregs—a unique type of cells with a regulatory function in the autoimmune disease model." (PMID 37895880, 2023). "Nevertheless, targeted depletion of NAC1 accelerated the acetylation of Foxp3, whereas overexpression of NAC1 can decrease the acetylation of Foxp3 and may lead to the progression of autoimmune disease." (PMID 37936703, 2023). "Infection is a type of disease that is different from autoimmune diseases and the suppressive function of FOXP3 T cells may be disadvantageous for hosts during infection." (PMID 37296126, 2023). "The decreased number of FOXP3+ T-reg lymphocytes we observed suggests that pathogenetic mechanisms similar to those that can lead to autoimmune diseases might also be involved in CD." (PMID 37175521, 2023). "Strategies targeting energy metabolism and FOXP3 splicing isoforms in Tregs may provide potential new approaches for the treatment of autoimmune diseases, inflammatory diseases, and cancers." (PMID 37868998, 2023). "Overall, Foxp3 CNSs could be targeted to develop complementary therapies and promote Treg cell functions in transplantation, autoimmune diseases, and chronic inflammation." (PMID 35812386, 2022). "However, therapies with the use of a targeted modification of the expression of the Foxp3 protein will certainly become a valuable tool in the future in the fight not only of autoimmune diseases but also of neoplastic diseases." (PMID 35207219, 2022).
autoimmune disease (continued). "Lack of FoxP3 in mice prevented the development of Treg cells and caused severe autoimmune disease, and forced FoxP3 expression turned Tconv cells into suppressive T cells." (PMID 35158783, 2022). "The affection of FOXP3 protein in quality or quantity leads to Treg cell dysfunction and impairs the balance between Th1 and Th2 cells, disturbing the immune system’s balance toward the development of immunological and autoimmune diseases." (PMID 35641708, 2022). "Uncontrolled FOXP3 ubiquitination has been proposed as a relevant mechanism in autoimmune diseases." (PMID 35296082, 2022). "However, homozygous Foxp3-Mettl14f/f cKO mice developed a severe autoimmune disease and died within eight to twelve weeks, similar to the results for Mettl3-Treg cKO mice." (PMID 36341394, 2022). "Our findings are consistent with observations from autoimmune disease models where FRCs indirectly restrain aberrant CD4+ T cell activation via MHCII presentation of self-antigen to induce proliferation of FoxP3+ Tregs and de novo conversion of Tregs in the mLNs under homeostatic conditions." (PMID 36227687, 2022). "When we generated Treg cell-specific OGT knockout (KO) using the Foxp3YFP-Cre mice with YFP-Cre knocked into the endogenous Foxp3 locus, hemizygous male KO mice developed scurfy phenotypes and died of autoimmune disease by the age of 4 weeks, thus preventing us to study their whole-body metabolism." (PMID 35874700, 2022). "Satb1 deficiency impairs CNS0 activation in human Treg cells, due to decreased demethylation, and consequently, Foxp3 activation, which might originate autoimmune diseases." (PMID 35812386, 2022). "It is well-known that Foxp3+ Tregs are critical for preserving immune tolerance and preventing immunopathology, and altered Treg composition and/or dysfunction can lead to severe chronic infections, oncogenesis, and autoimmune diseases." (PMID 36119090, 2022). "Additionally, mice thymectomized at day 3 after birth lack Foxp3+ Treg cells in the periphery and develop autoimmune diseases." (PMID 35563702, 2022). "Ongoing clinical trials with FOXP3+ Tregs in the field of kidney transplantation could provide useful hindsight for the therapeutic application of FOXP3+ Tregs in primary glomerulopathies and systematic autoimmune diseases of native kidneys." (PMID 34336285, 2021). "FOXP3 and GATA3 exert immune suppressive activity; however, some of their gene variants have been shown to impair immune-suppressive activity, thus contributing to the development of autoimmune diseases." (PMID 33806248, 2021). "For example, immune responses may be manipulated by modulating the expression of FOXP3 isoforms, which has broad implications for the treatment of autoimmune diseases." (PMID 34768829, 2021). "As an alternative strategy to control Tregs in vivo, we also used P60, a synthetic peptide that binds to FOXP3, a factor required for Treg development and function, thus inhibiting their function to protect against autoimmune diseases and prevent rejection of allogeneic transplants." (PMID 33568685, 2021). "Foxp3-expressing CD8+ Tregs have been reported to be important suppressive players in autoimmune disease such as type 1 diabetes and especially in the context of transplantation where donor cells continue to express MHCI for long time periods following the graft." (PMID 34630389, 2021). "Taken together, these results suggested that Helios in Tregs may regulate the development of autoimmune diseases in different orientations, and that FOXP3 expression in Helios− Tregs were more unstable in T1D individuals." (PMID 34054801, 2021). "Previous studies demonstrated that alteration of FOXP3 expression and functions could contribute to various autoimmune diseases due to a functional block of Treg cells." (PMID 33686190, 2021).